MIF (macrophage migration inhibitory factor)
Diseases named in the same sentence as MIF in open-access papers (continued):
Sharing a sentence is not in itself a finding about the gene and the disease.
melanoma (continued). "Similar findings were also obtained when considering anchorage-independent growth where it was shown that MIF siRNA transfection significantly compromised the number and size of colonies formed by melanoma cells." (PMID 25168062, 2014). "We also establish that in clinical melanoma samples, MIF expression increases with metastatic progression and is correlated with survival for metastatic melanoma patients." (PMID 25168062, 2014). "In the present report we adopted an siRNA-based strategy to examine the function of endogenous MIF expression in multiple human melanoma cell lines." (PMID 25168062, 2014). "Since the overall importance of the PI3K/Akt pathway to melanoma biology cannot be understated, these findings imply clinical significance of MIF signalling in this disease." (PMID 25168062, 2014). "Taken together, these results highlight the importance of the MIF-signalling axis with implications for targeted treatment approaches in melanoma." (PMID 25168062, 2014). "MIF has been identified as a serum marker for melanoma, and MIF is also elevated in colorectal cancer and a variety of other types of cancer." (PMID 22829910, 2012). "Approximately one-third of melanoma patients had elevated MIF and MLANA transcripts (p<0.0001 and p<0.001, respectively) compared with healthy controls." (PMID 22829910, 2012). "Both MLANA and MIF were significantly higher in melanoma patients (p<0.013 and p<0.0001, respectively)." (PMID 22829910, 2012). "We compared 2 groups of melanoma patients for changes in absolute MLANA levels vs. MIF levels based on time following surgery." (PMID 22829910, 2012). "Substantial increases in MLANA transcripts were observed in ∼ one-third of melanoma patients, accompanied by increases in MIF." (PMID 22829910, 2012). "With the MLANA and MIF targets, elevated levels were observed in a number of melanoma patients compared with healthy controls." (PMID 22829910, 2012). "In many tumor cells and pre-tumor states, for example, in prostate, colon, and hepatocellular cancers; adenocarcinomas of the lung; glioblastomas; and melanomas, increased MIF mRNA levels can be detected." (PMID 24281172, 2010). "The expression of MIF mRNA and the production of MIF protein have been shown to be substantially higher in human melanoma cells than in cultured normal melanocytes." (PMID 24281172, 2010). "We hypothesized that this naturally occurring variation in MIF expression could influence the development of human melanoma." (PMID 41122966, 2025). "In addition, poor response to immune checkpoint drugs is substantially correlated with high MIF expression; this is supported by patient data on melanoma that were derived from the TCGA database." (PMID 41159021, 2025). "High CD74 and low MIF expression correlated with improved survival outcomes and progression-free survival supporting the idea that the MIF−/CD74+ signature could serve as a prognostic marker in stage III melanoma." (PMID 41159021, 2025). "As biomarkers, MIF and CD74 were identified as key proteins associated with melanoma prognosis." (PMID 41159021, 2025). "Likewise, the macrophage migration inhibitory factor (MIF) is a diurnally regulated cytokine that peaks during early to late morning and upregulates PD-L1 expression in melanoma cells." (PMID 40075580, 2025). "Further studies are warranted to confirm this finding in additional cohorts and to define how intrinsic MIF expression may influence melanoma development, progression, or treatment response." (PMID 41122966, 2025). "IFN-γ promotes ultraviolet-mediated melanomagenesis and melanoma cell survival by regulating CD74-macrophage-migration inhibitory factor (MIF) signaling, leading to the activation of AKT phosphorylation and the expression of IL-6, IL-8, and B-cell leukemia/lymphoma-2 (BCL-2)." (PMID 40108693, 2025). "MIF was previously shown to be necessary for the immunosuppressive ME in melanoma and glioblastoma." (PMID 39576827, 2024).
melanoma (continued). "Additionally, this data is supported by prior animal studies suggesting a therapeutic effect of MIF or DDT antagonism in mouse models of melanoma." (PMID 39028303, 2024). "However, most literature on the MIF/CD74 axis in melanoma is limited to cell and animal studies, with few studies reporting on clinical outcomes." (PMID 39028303, 2024). "Potentially using combination therapy with both anti-CTLA-4 and a MIF inhibitor could increase immune cell infiltration in the tumor and reduce the expression of PD-L1 in melanoma cells." (PMID 38730725, 2024). "sCD74 and MIF levels were positively correlated in both melanoma patients and NHDs." (PMID 35121729, 2022). "Serum sCD74 levels were significantly elevated in advanced melanoma patients compared with normal healthy donors, and the high ratio of sCD74 to macrophage-migration inhibitory factor (MIF) conferred significant predictive value for prolonged survival in these patients (p = 0.0035)." (PMID 35121729, 2022). "Importantly, inhibition of MIF expression in melanoma stroma decreases the response of tumor cells to hypoxia, suppressing VEGF expression and MVD in tumor tissue." (PMID 35842634, 2022). "Overexpression of MIF has been identified in many different types of cancers such as cancer of the colon, lung, breast, prostate, bladder, and in glioblastoma, cervical adenocarcinoma, and melanoma." (PMID 35091838, 2022). "MIF is considered to be a determinant of melanoma MDSCs differentiation and immune suppression." (PMID 35842634, 2022). "Altogether, these results suggest the possible interaction between sCD74 and MIF, which may influence tumor progression in melanoma." (PMID 35121729, 2022). "Interestingly, the high expression of MIF in clinical studies of melanoma correlates with its more aggressive phenotype." (PMID 36123693, 2022). "The inhibition of CD74 and MIF could significantly attenuate the tumor growth of prostate cancer cells and melanoma mice model." (PMID 34540893, 2021). "In these studies, macrophage-derived MIF was necessary for maximal angiogenic growth factor expression in M2 alternatively activated macrophages and required for the T cell immunosuppressive capacity of melanoma-polarized TAMs." (PMID 33324425, 2020). "Local and metastatic uveal melanoma cell lines were found to secrete copious amounts of MIF with metastatic lines averaging more than 2x the MIF secretion as primary cells and this melanoma-derived MIF was protective in two of the cell line supernatants tested." (PMID 33324425, 2020). "Indeed, it has been reported that MIF production by melanoma cells leads to an induction of tube formation and the migration of endothelial cells, leading to the formation of new blood vessels in the tumor microenvironment." (PMID 31013837, 2019). "Although less data are available for DDT, which has been discovered more recently, several preclinical and clinical data have concordantly shown high levels of MIF in a variety of human cancers, including pancreatic and gastric cancer, melanoma, hepatocarcinoma, glioma and cervical adenocarcinoma." (PMID 31635049, 2019). "Indeed, despite its crucial role in tumor immune surveillance, IFN-γ has recently been shown to enhance the expression of the CD74 receptor of MIF in melanoma." (PMID 31013837, 2019). "A clinical study analyzed the MIF level in the serum of melanoma patients." (PMID 31013837, 2019). "These molecules have already given promising results, proving that targeting MIF could be effective in the treatment of many tumors, including melanoma." (PMID 31013837, 2019). "Indeed, the results reported in this review indicate that MIF is produced by melanoma cells and has a prognostic value in the case of metastatic melanoma." (PMID 31013837, 2019). "All these data indicate that MIF targeting could be a therapy of choice in the future of melanoma treatment." (PMID 31013837, 2019).
melanoma (continued). "Regarding their lack of toxicity and their effectiveness on melanoma and colon cancer cells, these kinds of MIF inhibitors could be very promising for the future of cancer therapy, and especially melanoma treatment." (PMID 31013837, 2019). "MIF produced by the surrounding stroma also acts on circulating myeloid-derived suppressor cells (MDSCs) which are responsible for the monocytic immunosuppressive activity that appears in late stage melanoma patients." (PMID 31013837, 2019). "MIF has also been identified as a key cytokine for TAM polarization in melanoma-bearing mice." (PMID 29618368, 2018). "MIF produced in the TME also regulates angiogenesis in a melanoma model." (PMID 26267609, 2015). "Additionally, in the B16-F10 mouse melanoma model, inhibition of MIF by RNAi significantly delayed tumour establishment when injected into mice." (PMID 25168062, 2014). "Dividing the samples into two groups, “early stage” (normal skin, benign and atypical naevi, melanoma in situ) and “advanced stage” (VGP and MGP melanomas, LN) demonstrated a statistically significant increase in MIF expression in “advanced-stage” tissue samples compared to the “early-stage” group." (PMID 25168062, 2014). "It seems probable that MIF expression in melanoma cells has an impact upon their proliferative capacity in vivo but whether the MIF gene expression detected in clinical samples is wholly tumour derived is not entirely clear." (PMID 25168062, 2014). "Overexpression of MIF has been reported in a number of cancer types and it has previously been shown that MIF is upregulated in melanocytic tumours with the highest expression levels occurring in malignant melanoma." (PMID 25168062, 2014). "We then sought to establish whether levels of MIF expression in melanoma were predictive of outcome by exploiting expression microarray data associated with clinical outcomes." (PMID 25168062, 2014). "However the relative importance of MIF production in melanoma tumour cells versus stromal cells remains to be established." (PMID 25168062, 2014). "Collectively this reinforces the idea that MIF signalling displays potential as a pathway that could be targeted for melanoma treatment." (PMID 25168062, 2014). "Despite these observations and previous work associating increased MIF with enhanced melanoma growth and metastasis in nude mice, the clinical significance of MIF tumour levels has surprisingly not been previously examined." (PMID 25168062, 2014). "Therefore, we examined the effects of MIF knockdown on the expression of key Akt-signalling components in melanoma cells." (PMID 25168062, 2014). "In the present study, we sought to establish the primary downstream signalling pathways activated by MIF in a panel of human melanoma cell lines in vitro using specific knock-down studies and determine the prognostic significance of MIF expression in metastatic melanoma." (PMID 25168062, 2014). "Notably, melanoma lines resistant to MIF depletion (MelRM and MM200) displayed minimal changes in Akt activity, while the most sensitive lines exhibited the greatest reduction in Akt activity, underscoring a positive correlation between MIF knockdown and Akt signaling." (PMID 41159021, 2025). "Furthermore, investigation of MIF and DDT expression levels across common melanoma mutational profiles using the Kruskal-Wallis test revealed enrichment across all groups, though findings were not statistically significant (MIF p = 0.12, DDT p = 0.88)." (PMID 39028303, 2024). "MIF’s role in subverting the immunogenic functions of DCs in melanoma highlights one of the potential key pathways melanoma cells might employ to evade immune surveillance, which has previously been overshadowed due to the focus on boosting GM-CSF levels artificially." (PMID 37454231, 2023).
melanoma (continued). "Moreover, blocking MIF-CD74 signaling could restore the antitumor immune response against metastatic melanoma and MIF inhibitors represented as a potential strategy to overcome resistance to ICB therapy in melanoma." (PMID 35558087, 2022). "Recent studies have shown that the interaction of MIF with its receptor CD74 has been associated to PD-L1 expression and IFN-γ production, thus favoring an immunosuppressive environment that may favor immunosuppression and tumor evasion in melanoma." (PMID 33401503, 2021). "In addition, TAM polarization following MIF blockade is another source of proof that targeting MIF could help in restoring immune response, attenuating melanoma progression and pulmonary metastases in patients." (PMID 31013837, 2019). "Regarding the fact that many melanoma patients carry a BRAF mutation, and that they develop resistance to BRAF inhibitors, this observation is very interesting as MIF inhibitors could be used to treat many patients in relapse after treatment with an inhibitor of the mutant BRAF protein." (PMID 31013837, 2019). "Indeed it has been indicated that many other melanoma cell types also produce MIF." (PMID 31013837, 2019). "Keeping in mind that many melanoma patients carry a BRAF mutation, and that they develop resistance to BRAF inhibitors, this observation is very interesting as MIF inhibitors could be used to treat many patients in relapse after a treatment with a mutant BRAF inhibitor." (PMID 31013837, 2019). "This analysis showed that MIF knockdown significantly reduced cells transitioning to the S-phase in four of the six melanoma cell lines suggesting the proliferative capacity of the majority of the melanoma cell lines studied have some degree of reliance on MIF expression." (PMID 25168062, 2014). "In MelCV and Me1007 cell lines, MIF knockdown resulted in significantly reduced cell number and viability over 6 days, indicating that endogenous MIF expression could be generally required for the growth of melanoma cells." (PMID 25168062, 2014). "Moreover, depletion of MIF inhibited melanoma proliferation, viability and clonogenic capacity." (PMID 25168062, 2014). "CD74′s prognostic value varies by tumor type: favorable in immune-inflamed cancers such as melanoma and HCC, but adverse in malignancies driven by MIF-mediated survival signals such as lymphomas and PDAC." (PMID 41597203, 2026). "Furthermore, high CD74 and MIF ratios correlated with increased pro-inflammatory markers and immune cell infiltration, suggesting that these ratios could serve as important indicators of immune response in melanoma." (PMID 41159021, 2025). "We first assessed anti-MIF and anti–PD-1 antibody treatments in C57BL/6J mice injected subcutaneously with YUMMER1.7 melanoma cells." (PMID 41122966, 2025). "The therapeutic efficacy of anti-MIF, alone or combined with anti–PD-1, was tested in the YUMMER1.7 melanoma and MC38 colorectal cancer models." (PMID 41122966, 2025). "Currently, targeting the MIF/CD74 axis is a promising strategy for treating and overcoming resistance to immune checkpoint blockade therapy in melanoma and modulating the TME to promote effective antitumor immunity." (PMID 39028303, 2024). "Specifically, overexpression of MIF contributed to tumor progression and the immune escape mechanism of HCC, ovarian carcinoma, and melanoma." (PMID 38638429, 2024). "We recommend proceeding with clinical trials of anti-MIF and -DDT agents, with an emphasis on cancer types supported by strong preclinical and clinical evidence for MIF and DDT involvement, such as melanoma." (PMID 38732068, 2024). "Genetic, transcriptomic, and proteomic analyses of DDT, CD74:MIF, and CD74:DDT in patients with melanoma can further shed light on the differential expression among varying disease stages, tumor subtypes, mutational statuses, and ICI use." (PMID 39028303, 2024).
melanoma (continued). "Taken together, MIF and DDT offer potential as therapeutic targets in patients with melanoma, including patients who progress on existing immune therapies." (PMID 39028303, 2024). "Herein, we present the first study to retrospectively evaluate differential gene expression of MIF, DDT, and relevant pathway markers in regard to clinical outcomes in patients with melanoma." (PMID 39028303, 2024). "Our data bolsters existing evidence on the intratumoral effects of MIF and DDT on tumor permissiveness, primarily through immune modulation, with evidence translating to melanoma prognosis." (PMID 39028303, 2024). "Taken together, our data suggests measurement of CD74:MIF and CD74:DDT expression level ratios can provide prognostic information with respect to survival in patients with autoinflammatory disease and melanoma better than MIF, DDT, or CD74 alone." (PMID 39028303, 2024). "Previous studies have found that inhibiting MIF/CD74 signaling pathway can suppress AKT phosphorylation and promote tumor development in melanoma and esophageal squamous cell carcinoma." (PMID 38685050, 2024). "Previous studies reported that compared with NMM, the expression levels of SNAI2, MMP2, MIF, and AP1S2 were up-regulated in MM and were crucial roles in the metastasis and malignant progression of melanoma." (PMID 37880239, 2023). "Another CDR cyclic peptide formulation (Rb9) also exhibited immunomodulatory effects on DCs by disturbing MIF/CD74 axis, boosting melanoma immunogenicity, when treating advanced lung metastasis." (PMID 37454231, 2023). "Six STAT3-inducing cytokines (IL-6, IL-11, MIF, PDGF-AA, OPN, and MCP-1), all expressed by melanoma, were tested for their ability to induce these alterations in microglia cells." (PMID 37296634, 2023). "EVs derived from hypoxic melanoma cells are enriched in a range of pro-tumorigenic and immunosuppressive factors, including TGF-β1, TGF-β2, TGF-β3, macrophage migration inhibitory factor (MIF), and ferritin heavy/light chain (FTH/FTL)." (PMID 36010994, 2022). "MIF interacts with its receptor CD74 to activate the IFNγ-JAK-STAT pathway, resulting in significant upregulation of PD-L1 in melanoma cells, which aids in tumor cell escape from the immune response and maintenance of immunosuppressive TME." (PMID 35842634, 2022). "Both recombinant and THP-1 macrophage-released endogenous sCD74 suppressed melanoma cell growth and induced apoptosis under IFN-γ stimulatory conditions via inhibiting the MIF/CD74/AKT-survival pathway." (PMID 35121729, 2022). "Our present work suggests that sCD74 displayed moderate antiproliferative capacity, by acting as a “decoy” receptor for MIF, and was antagonistic to the MIF/CD74/AKT-survival signaling pathway in melanoma." (PMID 35121729, 2022). "Macrophage migration inhibitory factor (MIF) is involved in diseases through protein-protein interactions in cancers and inflammations such as melanoma, neuroblastoma, and lung cancer." (PMID 36142231, 2022). "Apart from melanoma, CD74 and MIF have been considered as therapeutic targets in other cancer types such as prostate cancer and gastric cancer." (PMID 35769782, 2022). "Along this line of research, several studies by ourselves and others have proposed a pathogenetic role of MIF, and possibly DDT, in certain cancers such as melanoma, neuroblastoma, head and neck cancer, and glioblastoma." (PMID 33401503, 2021). "Molecular target CD74 is a highly expressed membrane receptor on the surface of dendritic cells (DC) and macrophages (MP) and shows a high affinity for the macrophage migration inhibitory factor (MIF), which is highly expressed by melanoma cells." (PMID 34445599, 2021). "We have previously observed weakened outcomes in patients with constitutive expression of inducible nitric oxide synthase (iNOS), macrophage migration inhibitory factor (MIF) and improved outcomes with CD74 expression in stage III melanoma." (PMID 33327409, 2020).